VDR (vitamin D receptor)
Diseases named in the same sentence as VDR in open-access papers (continued):
Sharing a sentence is not in itself a finding about the gene and the disease.
psoriasis (continued). "This study was conducted to investigate whether VDR polymorphisms could be susceptibility markers for psoriasis." (PMID 34208603, 2021). "In patients with psoriasis, resistance to treatment with vitamin D was observed, which may be due to VDR gene polymorphisms." (PMID 34208603, 2021). "Therefore, this study aimed to evaluate the association of VDR polymorphisms with susceptibility to psoriasis, effectiveness of NB-UVB phototherapy and concentration of proinflammatory cytokines and vitamin D amongst the Polish population." (PMID 34208603, 2021). "The rs7975232 ApaI variant of VDR may be associated with the development of inflammatory disease, such as oral lichen planus and psoriasis in the Asian population." (PMID 34208603, 2021). "In our updated meta-analysis of VDR rs7975232, we enrolled thirteen case-control studies for pooling and did not detect any significant statistical association between the VDR rs7975232 polymorphism and the odds of psoriasis." (PMID 31623568, 2019). "The hypothesis on the role of vitamin D3 deficiency in the pathogenesis of psoriasis may be supported by the fact that the A-1012G polymorphism of the VDR receptor gene associated with lower VDR mRNA expression is more frequently detected in psoriasis patients." (PMID 39598018, 2024). "Moreover, VDR polymorphisms could be susceptibility markers for psoriasis and effectiveness of UVB therapy." (PMID 34208603, 2021). "We observed that etanercept treatment led to a significant decrease in VDR expression in the perilesional dermis of one psoriasis patient." (PMID 40699711, 2025). "This genotype-dependent dysregulation likely arises from altered VDR-mediated transcriptional control of IL17A and IL23A loci, implicating VDR polymorphisms as modifiers of IL-23/Th17 axis hyperactivity in psoriasis pathogenesis." (PMID 40681996, 2025). "Collectively, these studies suggest that VDR is significantly involved in the pathophysiology of psoriasis." (PMID 40699711, 2025). "Psoriasis clinical trials primarily investigate vitamin and hormone regulation mechanisms, with vitamin D receptor (2 trials) identified as the main target." (PMID 40777013, 2025). "Further research is essential to deepen our understanding of the role of VDR in psoriasis pathogenesis and to determine its potential as a therapeutic target." (PMID 40699711, 2025). "The azobenzene-containing agonist of the vitamin D receptor, PhotoVDRM, enables spatiotemporal psoriasis treatment in mice; its cisoid form induces potent anti-inflammation without hypercalcemia." (PMID 41476763, 2025). "The primary aim of this study was to examine if VDR expression on peripheral blood mononuclear cells (PBMCs) differs between patients with psoriasis and healthy controls." (PMID 39409006, 2024). "On the other hand, despite varying levels of VDR expression over time, patients with psoriasis exhibited a positive response to the Etanercept treatment, as evidenced by a decrease in PASI scores." (PMID 39409006, 2024). "VDR expression on CD14+ monocytes was higher in patients with psoriasis compared to healthy controls at baseline (p = 0.015)." (PMID 39409006, 2024). "We observed higher expression of the VDR on CD14+ monocytes in psoriasis patients compared to healthy controls at baseline." (PMID 39409006, 2024). "For instance, VDR is targeted by calcitriol, a Vitamin D receptor agonist that is currently used to treat various diseases such as cancers, psoriasis, and atopic eczema." (PMID 38182794, 2024). "In this prospective observational study, we observed a significant difference in VDR expression on CD14+ monocytes when comparing patients with psoriasis and healthy controls at baseline, with a higher expression in the psoriasis group." (PMID 39409006, 2024). "Patients with moderate to severe psoriasis had higher VDR expression on CD14+ cells compared to healthy controls." (PMID 39409006, 2024).
psoriasis (continued). "In patients with psoriasis, VDR is expressed abnormally low in keratinocytes, and its expression levels are significantly negatively correlated with the severity of the disease (Chandra, Roesyanto-Mahadi & Yosi, 2020)." (PMID 37554338, 2023). "The vitamin D receptor (VDR) has a low level of expression in the keratinocytes of patients with psoriasis and plays a role in the development of the disease." (PMID 37554338, 2023). "Studies using a murine model of psoriasis‐like inflammation demonstrated that the expression of the vitamin D receptor (VDR) exhibits diurnal variation with VDR levels peaking in the middle of the active period (night‐time for nocturnal animals such as mice)." (PMID 35851722, 2022). "It has been reported that serum 25-hydroxyvitamin D3 levels are reduced in patients with psoriasis or psoriatic arthritis compared to controls and that the expression of VDR is decreased in psoriatic skin lesions." (PMID 34501328, 2021). "In our study, we analyzed an association between one of the VDR gene polymorphisms, level of TNF, IL-17, IL-23, vitamin D and psoriasis in the Polish population." (PMID 34208603, 2021). "The vitamin D3 analogue calcipotriol used in treating psoriasis inhibited IL-23/IL-17 axis and neutrophil infiltration in psoriatic skin through the vitamin D receptor (VDR) in keratinocytes." (PMID 34208603, 2021). "For example, VDR activation by the use of vitamin D analogues and the blocking of IL-17 signaling are widely used in the treatment of psoriasis." (PMID 34877506, 2021). "The aim of our paper is to perform an association study between VDR polymorphism, proinflammatory cytokine and vitamin D levels, and individual response to NB-UVB phototherapy commonly used in the treatment of psoriasis." (PMID 34208603, 2021). "This is the first report of a relationship between VDR polymorphisms and response to UVB treatment of psoriasis." (PMID 34208603, 2021). "Skin toxicity is a common side-effect of a variety of drug types including the vitamin D receptor (VDR) agonist calcitriol and its analogue calcipotriol, both of which are used to treat psoriasis." (PMID 33023184, 2020). "The study aims at scientifically investigating the genetic effect of four polymorphisms (rs7975232, rs1544410, rs2228570, and rs731236) within the human Vitamin D Receptor (VDR) gene on the odds of psoriasis through an updated meta-analysis." (PMID 31623568, 2019). "Other genes associated with psoriasis include signal transducer and activator of transcription 4 (STAT4), apoliprotein E (APOE), vitamin D receptor (VDR), and cytotoxic T lymphocyte-associated protein 4 (CTLA4)." (PMID 24069534, 2013). "Despite the many advantages so far summarized, the use of VDR agonists in clinics is until now limited to calcipotriol, a vitamin D analogue topically applied for the treatment of psoriasis." (PMID 23690671, 2013). "There are several polymorphisms associated with risk of psoriasis, including signal transducer and activator of transcription 4 (STAT4), TaqI polymorphisms in vitamin D receptor (VDR) gene, interleukin-10 (IL-10) polymorphisms and LCE3B genes." (PMID 24324571, 2013). "As vitamin D3 analogs activate the vitamin D receptor, we would expect that they induce cathelicidin presumably aggravating inflammation in psoriasis." (PMID 20182640, 2009). "In addition, several genetic studies have identified multiple susceptibility loci for psoriasis, including psoriasis susceptibility region 1 (PSORS1), IL12B, and the vitamin D receptor (VDR) gene." (PMID 41465136, 2025). "Importantly, testing PhotoVDRM ina psoriasis mouse model demonstrates that it can spatiotemporallyactivate VDR in localized diseased areas." (PMID 41473792, 2025). "Vitamin D receptor (VDR) activation has demonstratedbeneficialeffects on psoriasis." (PMID 41473792, 2025).
psoriasis (continued). "In the same study, they also found that VDR expression levels were associated with the clinical severity of liver disease; however, we did not observe a similar relationship in patients with psoriasis." (PMID 39409006, 2024). "Given the fact that vitamin D can regulate the proliferation of keratinocytes, VDR impairment in epidermal skin could have a potential role in the pathogenesis of psoriasis, explaining why further research in this topic is necessary." (PMID 39409006, 2024). "This aligns with our results showing higher VDR expression on CD14+ cells in patients with psoriasis compared to healthy controls, indicating that disease severity and inflammation might impact VDR expression." (PMID 39409006, 2024). "This study aimed to evaluate vitamin D receptor (VDR) expression on peripheral blood mononuclear cells (PBMCs) in patients with psoriasis and healthy controls and to study the effects of the Etanercept treatment on VDR expression on PBMCs in patients with psoriasis." (PMID 39409006, 2024). "Furthermore, the activation of VDR inhibits psoriasis-like skin inflammation by suppressing signal transducer and activator of transcription (STAT) signaling pathway." (PMID 37554338, 2023). "Calcipotriol, a vitamin D receptor agonist, is the topical gold standard for the treatment of psoriasis and is able to reverse cisplatin resistance and enhance the efficacy of PD1 antibodies in the treatment of pancreatic ductal adenocarcinoma in gastric cancer." (PMID 37762693, 2023). "Other psoriasis-linked genes include APOE, CTLA4, DEFB4, GBP6, LCE, MCP1, VDR, and ZNF313." (PMID 37569685, 2023). "The rs1544410 (BsmI) polymorphism in the vitamin D receptor (VDR) gene did not influence the response to calcipotriol in 92 English patients with psoriasis." (PMID 37372997, 2023). "None of the VDR polymorphic variants analyzed in the experiment were found to be related with extra-articular manifestations, such as uveitis, enthesitis, psoriasis, or inflammatory bowel disease (IBD)." (PMID 36292758, 2022). "Deregulation of VDR function may lead to severe diseases, such as cancers, psoriasis, rickets, renal osteodystrophy, and autoimmunity disorders (multiple sclerosis, rheumatoid arthritis, inflammatory bowel diseases, type I diabetes)." (PMID 35889804, 2022). "A meta-analysis of 11 studies revealed that FokI and ApaI VDR polymorphisms are not linked to psoriasis risk, but the BsmI B variant shows borderline association." (PMID 35955731, 2022). "One vitamin D3 analog, calcipotriol (CPT), inhibits cellular DNA and keratin synthesis by binding specifically to the vitamin D receptor (VDR), allowing correction of abnormal keratinocytes proliferation and differentiation is used as a primary topical agent for psoriasis." (PMID 35748409, 2022). "Since vitamin D can regulate the proliferation and growth of keratinocytes, the impairment of VDR expression in epidermal skin cells could be involved in the pathogenesis of psoriasis." (PMID 35955731, 2022). "The reduced levels of vitamin D3 and/or VDR may be related to defects in Tregs in psoriasis via the reduction of Foxp3 expression." (PMID 34501328, 2021). "Our data failed to support the essential role of the VDR rs7975232 polymorphism in the odds of psoriasis, which is in line with the data of Lee, YH.." (PMID 31623568, 2019). "Above all, based on the presently available case-control studies, our pooling analysis data and previous reports do not provide the robust statistical evidence linking VDR rs7975232, rs1544410, and rs2228570 polymorphisms with the odds of psoriasis." (PMID 31623568, 2019). "The currently available data fails to support a robust association between VDR rs7975232, rs1544410, rs2228570 and rs731236 polymorphisms and psoriasis susceptibility, which still required the support of more case-control studies." (PMID 31623568, 2019).
psoriasis (continued). "One approach to enhancing topical therapies for psoriasis is therefore to identify key genes affected by treatment as well as VDR analogs or other ligands that may optimize these effects." (PMID 29401702, 2018). "Several authors have demonstrated the role of VDR in the pathogenesis of psoriasis." (PMID 24069534, 2013). "Studying different haplotypes rather than a single VDR gene polymorphism could be more helpful in understanding the pathophysiological mechanism of the VDR gene in the development of psoriasis." (PMID 36686134, 2023). "However, the VDR rs7975232 polymorphism was not considered a risk factor for psoriasis cases in Japan, Italy, Croatia, or Egypt." (PMID 31623568, 2019). "In addition, the A allele in rs451635 (VDR gene) was protective against susceptibility to nonfamilial psoriasis." (PMID 24069534, 2013). "In the present study, we observed great individual variations in VDR expression (%) on both CD3+ and CD14+ cells among patients with psoriasis and in healthy controls, both at baseline and after 24 weeks." (PMID 39409006, 2024). "On the other hand, we found a positive correlation between VDR expression on CD3+ lymphocytes and CD14+ monocytes in patients with psoriasis before the treatment’s start, which ceased to be significant after 24 weeks of the Etanercept treatment." (PMID 39409006, 2024). "We found a positive correlation between VDR expression on CD3+ lymphocytes and CD14+ monocytes in patients with psoriasis at baseline." (PMID 39409006, 2024). "There was a significant positive correlation between VDR expression on CD3+ lymphocytes and CD14+ monocytes in patients with psoriasis at baseline (p = 0.0005)." (PMID 39409006, 2024). "Recent studies have also found interleukin 1β (IL-1β), tumor necrosis factor (TNF), vitamin D receptor (VDR), nitric oxide synthase 3 (NOS3), and other genes to be overexpressed in psoriasis patients (GOF)." (PMID 29292715, 2017). "There is a clear need for larger cohort studies to validate these observations and to address the lack of consensus in the literature regarding VDR expression in psoriasis." (PMID 40699711, 2025). "TNF alpha concentration in patients with psoriasis decreases after UVB irradiation, independent of polymorphisms in the VDR gene, except for the presence of the TaaI/Cdx-2 AA genotype and TaqI TT genotype." (PMID 34208603, 2021). "This analysis produced a list of 9 significantly altered canonical pathways (p < 0.05 or –log p-value > 1.30) including SAPK/JNK signaling, NAD biosynthesis and salvage pathway, phototransduction pathway, VDR/RXR activation, Reelin signaling in neurons, and role of IL-17A in psoriasis." (PMID 32260415, 2020). "1,25(OH)D, 1,25-hydroxyvitamin D or calcitriol; 25OHD, 25-hydroxyvitamin D; BMI, body mass index; CRP, C -reactive protein; IL, interleukin; MetS, metabolic disease; PASI, psoriasis area and severity index; RDAs, recommended dietary allowances; TNF, tumor necrosis factor; VDR, vitamin D receptor." (PMID 28176237, 2017). "Nevertheless, the use of VDR agonists in clinics is generally not pursued and is limited to calcipotriol, a drug applied for psoriasis topic treatment." (PMID 24895631, 2014). "This study aimed to analyze VDR mRNA expression in psoriatic skin tissue before and after etanercept therapy using RNAscope, an RNA in situ hybridization technique that, to the best of our knowledge, has not previously been applied in psoriasis research." (PMID 40699711, 2025). "This suggests that VDR expression on PBMCs might not be correlated with the severity of psoriasis." (PMID 39409006, 2024). "Treatment with Etanercept did not alter VDR expression on CD3+ and CD14+ cells in patients with psoriasis over the 24-week period (p = 0.99, p = 0.96)." (PMID 39409006, 2024). "The Etanercept treatment improved the disease but did not alter VDR expression on CD3+ lymphocytes and CD14+ monocytes in patients with psoriasis." (PMID 39409006, 2024).
psoriasis (continued). "The aim of this study was to investigate VDR expression in psoriatic skin tissue before and after etanercept treatment by using RNAscope, a novel RNA in situ hybridization (ISH) technique not previously applied in psoriasis research." (PMID 40699711, 2025). "Treatment with Etanercept for 24 weeks did not alter VDR expression on CD3+ and CD14+ cells in this cohort of patients with psoriasis with sufficient serum vitamin D levels at the treatment’s start, implying that VDR expression might not be related to disease severity or the grade of inflammation." (PMID 39409006, 2024).